PGR (progesterone receptor)
Diseases named in the same sentence as PGR in open-access papers (continued):
Sharing a sentence is not in itself a finding about the gene and the disease.
breast cancer (continued). "The PAM50, gene expression classifier which has been used to group breast cancers into Luminal A, Luminal B, Basal, and Her2-like subsets; the luminal breast cancer subtypes express higher levels of estrogen receptor and progesterone receptor and are more responsive to hormonal therapy." (PMID 31366128, 2019). "PgR should be considered in evaluating the prognosis of breast cancer patients using Ki-67." (PMID 31975992, 2019). "Progesterone receptor (PR) action in breast cancer and TGFβ signaling via miRNA in breast cancer were identified as pathways downstream of the upregulated miRNAs, and TGFβ signaling via SMADs and activation of Notch signaling were identified as pathways downstream of the downregulated miRNAs." (PMID 31263129, 2019). "MetaCore Enrichment analysis identified progesterone receptor action and transforming growth factor β (TGFβ) signaling via miRNA in breast cancer as pathways downstream of the upregulated miRNAs and TGFβ signaling via SMADs and Notch signaling as pathways of the downregulated miRNAs." (PMID 31263129, 2019). "We investigated the effects of JEKHT on ER and PgR in mammary tumors in the preclinical model." (PMID 30640711, 2019). "Breast cancer is the most common cancer among women worldwide, and approximately 70% of breast cancers are hormone receptor-positive and express estrogen receptor-α (ERα) or/and progesterone receptor." (PMID 30658681, 2019). "Thus, PgR expression should also be considered in evaluating the prognosis of breast cancer patients using Ki-67." (PMID 31975992, 2019). "Breast cancer (BC) is the most frequent neoplasm among women, and it is classified into four different subtypes based on the estrogen receptor (ER), progesterone receptor (PgR), and Human Epidermal growth factor Receptor 2 (HER2) expression." (PMID 31450618, 2019). "One of the most prominent classifications of breast cancer tumors is whether they express the estrogen receptor (ER), progesterone receptor (PR), or human epidermal growth factor receptor 2 (HER2)." (PMID 30759745, 2019). "In this study, we investigated the relationships of pathological response after neoadjuvant chemo-endocrine therapy with alterations in the Ki67 labeling index (LI), expression of cyclin D1 (CCND1) and progesterone receptor (PgR), and estrogen receptor (ER) activity in breast cancer." (PMID 31112577, 2019). "However, breast cancer is still generally assessed based on the expression of estrogen receptor (ER), progesterone receptor (PR), and HER2." (PMID 31058868, 2019). "Furthermore, the correlation of PNPO expression with the breast cancer hormone therapy-related markers such as estrogen receptor (ER), progesterone receptor (PR) and human epidermal growth factor receptor-2 (HER2) is not clear." (PMID 30982780, 2019). "This analysis revealed that in general, ESR1 expression exhibits a negative correlation with FAM171A1 in breast cancer datasets, and a similar trend was also observed for PGR in respective cell lines as well as carcinoma databases other than breast cancer datasets." (PMID 30631046, 2019). "Classic prognostic markers in breast cancer include tumor size, histologic grade (HG), estrogen receptor (ER), and progesterone receptor (PR), Ki67 proliferation index, human epidermal growth factor receptor type 2 (HER2) protein and axillary lymph node (N) status." (PMID 31595254, 2019). "Thus, other studies suggested that ER−/PgR+ breast carcinomas show definite clinical and biological features." (PMID 30066060, 2019). "In conclusion, among the 9844 patients, the largest series in Japan, 27 (0.3%) were initially diagnosed as ER−/PgR+ breast carcinomas, and the ER−/PgR+ phenotype was still present after the re-evaluation of ER and PgR using whole sections recut from the same tissue block." (PMID 30066060, 2019). "PgR expression in breast carcinoma may potentially define a distinct subgroup with paired function in the ER pathway that will probably benefit from endocrine therapy." (PMID 30066060, 2019).
breast cancer (continued). "Moreover, there were several reports showing the gene-expression profile of ER−/PgR+ breast carcinomas." (PMID 30066060, 2019). "Breast cancer can be classified into five subtypes based on gene expression profiling and immunohistochemical expression of estrogen receptor α (ERα), progesterone receptor (PR), and human epidermal growth factor receptor 2 (HER2): luminal A, luminal B, HER2, and basal- and normal-like." (PMID 29416640, 2018). "Moreover, it has been reported that MDA-MB-231 breast cancer cells are not only ERα- but also progesterone receptor (PgR) and human epidermal growth factor receptor 2 (HER-2) negative." (PMID 30423956, 2018). "Other similar predictive biomarkers also exist in other cancers, such as the detection of oestrogen and progesterone receptor expression to predict the response to hormone therapies in breast cancer, and the detection of HER-2 to predict the response to trastuzumab therapy, also in breast cancer." (PMID 30513835, 2018). "However, in routine clinical practice, breast cancer subtype is commonly approximated using the surrogate immunohistochemistry (IHC) markers, oestrogen receptor (ER), progesterone receptor (PR), human epidermal growth factor receptor 2(HER2) and Ki67." (PMID 30034522, 2018). "Triple-negative breast cancer (TNBC), an aggressive subtype of breast cancer, is characterized by deficiency of estrogen receptor (ER), progesterone receptor (PR), and human epidermal growth factor receptor-2 (HER2)." (PMID 29316690, 2018). "Breast cancer can be divided into subtypes according to histopathological features such as progesterone receptor (PR), estrogen receptor (ER), or erb-b2 receptor tyrosine kinase 2 (ERBB2 or HER2) status, and include ER-positive, HER2-positive, or triple-negative breast cancer." (PMID 30326937, 2018). "In our study, we also used IHC analysis to evaluate TOP2A overexpression as a significant prognostic factor in luminal breast cancer; however, the prognostic value was restricted in luminal B breast cancer, defined as tumors with high Ki67 index and/or low PgR expression." (PMID 29928479, 2018). "Ten percent of breast cancers are ER/progesterone receptor (PR)-positive and human epidermal growth factor receptor 2 (HER2)-positive, 69% are ER/PR-positive and HER2-negative, 7% are ER/PR-negative and HER2-positive, and the remaining 13% are classified as triple-negative." (PMID 29783719, 2018). "High vs. low expression of VEGFR1 protein was deemed unfavorable for the risk of relapse in the TNBC subgroup (HR = 2.74, 95% CI 1.26–5.98, p = 0.011), whereas the opposite was observed among the ER/PgR positive breast cancer patients (HR = 0.69, 95% CI 0.48–0.98, p = 0.041)." (PMID 30063723, 2018). "Moreover, overexpression of CK18 was highly relevant to advanced clinicopathological parameters of breast cancer, such as progesterone receptor, human epidermal growth factor receptor-2, tumor size, tumor stage, nodal status, and tumor grade." (PMID 29437899, 2018). "For example, in breast cancer, LATS2 mRNA expression was downregulated by promoter hypermethylation and this alteration was associated with large tumour size, high rate of metastasis and estrogen receptor and progesterone receptor negativity." (PMID 30046387, 2018). "Furthermore, we also compared SALL1 expression in breast cancer patients with different hormone receptors, estrogen receptor (ER) and Progesterone receptor (PR), or HER2 expression statuses." (PMID 29625565, 2018). "However there is evidence that the fraction of infiltrating immune cells, and more specifically lymphocytes, are associated with better prognosis in TNBC as well as estrogen and progesterone receptor positive (ER+; PR+) breast cancer subtypes." (PMID 29805773, 2018). "In breast cancer, the overexpression of AURKA is also linked to poor survival and it is associated with the overexpression of the human growth factor receptor 2 (HER2) and progesterone receptor." (PMID 30070631, 2018).
breast cancer (continued). "Second, PgR expression and Ki67 index were substituted for a multigene expression classifier, such as Oncotype Dx or Mammaprint, to distinguish luminal B from luminal A breast cancer in this study." (PMID 29928479, 2018). "The degradation of ER and PgR has been shown to be under the control of the ubiquitin proteasome system, and recent research revealed that the phosphorylation of ERα via p38 activation promotes ERα turnover in breast cancer cells." (PMID 30347895, 2018). "GREB1 and PGR play a critical role in ERα genomic activity in breast cancer cells." (PMID 29608602, 2018). "We demonstrated that SALL1 functions as a tumor suppressor in breast cancer, which is significantly down-regulated in the basal like breast cancer and in estrogen receptor (ER), progesterone receptor (PR) and epidermal growth factor receptor 2 (HER2) triple negative breast cancer patients." (PMID 29625565, 2018). "Large-scale studies using only ER-negative or triple-negative (i.e., ER-, progesterone receptor-, and HER2-negative) cases could therefore be helpful to confirm the association of this locus with breast cancer risk." (PMID 27796716, 2017). "The ER+PgR+ and ER-PgR- are the most common subgroups in women with breast cancer in Ivory Coast." (PMID 28173783, 2017). "Although the immunohistochemical evaluation of ER and PgR is a routine clinical practice in the diagnosis and treatment of breast cancer management worldwide, the clinical utility of ER and PgR testing in breast cancer is currently performed since June 2013 in Ivory Coast." (PMID 28173783, 2017). "On the other hand, the molecular classification of breast cancer is based on protein expression patterns involving several markers such as estrogen receptor (ER), progesterone receptor (PR), human epidermal growth factor receptor 2 (HER2), HER1 and basal cytokeratin." (PMID 28538673, 2017). "Proliferation may predict response to neoadjuvant therapy of breast cancer and is commonly assessed by manual scoring of slides stained by immunohistochemistry (IHC) for Ki-67 similar to ER and PgR." (PMID 28193205, 2017). "Epidermal growth factor (EGF) is a crucial factor in mammary gland development and EGFR-targeted therapy provides some promising effects in patients with triple-negative (estrogen receptor-, progesterone receptor-, and erb-b2 receptor tyrosine kinase 2-negative) breast cancer." (PMID 29212252, 2017). "In the past decades, several biomarkers were discovered, for example, epidermal growth factor receptor (EGFR) in lung cancer patients and hormone receptor (HR), human epidermal growth factor receptor 2 (HER2), estrogen (ER), progesterone receptor (PR) in breast cancer patients." (PMID 29228627, 2017). "Thus our index study attempts to elucidate the pattern of ER, PgR and HER-2 expression as well as associated factors among women with breast cancer at MNH." (PMID 29142588, 2017). "The ER/PgR status is essential for clinical and therapeutic care of the breast cancer patients." (PMID 28173783, 2017). "In addition to their classification by gene profiling analysis, was divided breast cancer according to estrogen receptor (ER), progesterone receptor (PR), and HER-2 into another subgroup, triple-negative breast cancer (TNBC)." (PMID 29261141, 2017). "Furthermore, we classified the breast cancer tissues into ER-positive, PgR-positive, HER2-negative breast cancer (EP+H-) and TN, and then the differences in their metabolic pathways were investigated." (PMID 28851309, 2017). "Breast cancers were predominantly oestrogen receptor- and progesterone receptor-positive." (PMID 29708200, 2017). "Over-expression of ER and/or PgR are found in approximately 70–80% of all breast cancer cases." (PMID 28509845, 2017). "BRCA1 mutated breast cancers are commonly diagnosed as negative for classical hormone receptors i.e. estrogen receptor, progesterone receptor and/or Her2." (PMID 28427429, 2017).
breast cancer (continued). "Additionally, a significant association between cluster membership and ER/PgR status, HER2 status, basal phenotype and breast cancer subtypes was observed (Chi-square, all p-values <0.001)." (PMID 28797035, 2017). "This patient was diagnosed at the age of 54 with an ER-/PgR-/HER2-primary breast cancer." (PMID 28429735, 2017). "In the present study, we investigated the prognostic utilities and most suitable cut-off values for Ki67 LI and PgR expression, and then analyzed the relationship between Ki67 LI and PgR expression as a prognostic marker in patients with ER-positive/HER2-negative breast cancer." (PMID 28532429, 2017). "Furthermore, we evaluated differences in the metabolome between TN and breast cancer tissue samples that were ER- and PgR-positive, but HER2-negative (designated as EP + H-)." (PMID 28851309, 2017). "Prior studies including ours have suggested that expression levels of estrogen receptor (ER), progesterone receptor (PR), IGF-1 receptor (IGF-1R), and Ki67 in cancer-free breast tissue may be associated with subsequent breast cancer risk." (PMID 28979927, 2017). "Breast cancers can be subdivided into three clinically distinct subtypes based on the expression of specific receptors (estrogen receptor (ER)/progesterone receptor (PR) positive, Her2/Neu or triple negative), all of which have the capacity to metastasize to the bone." (PMID 28968431, 2017). "The Roche-Hoffman Laboratory in Ivory Coast, in collaboration with the Ivorian Health Ministry, has recently offered a Unit of Immunohistochemistry to the Central Laboratory to investigate the ER/PgR status of breast cancer patients for an efficient medical support." (PMID 28173783, 2017). "We aimed to explore the association between lifetime passive smoking and risk of breast cancer subtypes defined by estrogen receptor and progesterone receptor status among non-smoking Caucasian women." (PMID 28151962, 2017). "Published reports open a question whether the altered biology of ER + PgR- breast cancers results from dysfunctional ER molecules (unable to promote the PgR expression)." (PMID 28356061, 2017). "As a highly heterogeneous malignancy, breast cancer can be classified into four subtypes based on the expression of specific biomarkers estrogen receptor (ER), progesterone receptor (PR), human epidermal growth factor receptor-2 (HER2), and proliferation marker Ki-67." (PMID 29132385, 2017). "For breast cancer, levels and extent of oestrogen receptor (ER), progesterone receptor (PR, as a marker of ER function) and HER2 are used to broadly categorize a tumour and inform on the benefit of anti-estrogen agents (e.g., tamoxifen) or tyrosine kinase inhibitors." (PMID 28117763, 2017). "The progesterone receptor (PR) is an estrogen response element that is transcribed after effective binding of the estradiol-estradiol receptor (ER) complex to DNA in ER-positive, estradiol-responsive breast cancers." (PMID 27822700, 2017). "Progesterone receptor (PR) status should be considered in classification of breast cancer." (PMID 26848530, 2016). "Sections from these TMAs were stained and analyzed using immunohistochemistry to detect clinical breast cancer markers, including estrogen receptor (ER), progesterone receptor (PR), human epidermal growth factor 2 receptor (HER2) status, Ki67, and immune cell markers." (PMID 26964534, 2016). "Although the majority of breast cancers are ER-positive and approximately 25–30% are ER-negative, current chemotherapeutic strategies for breast cancer treatment commonly rely on the expression of important biomarkers such as estrogen receptor (ER), progesterone receptor (PGR) and HER2 protein." (PMID 27159275, 2016). "Less is known regarding whether survival outcomes are influenced by age at diagnosis of breast cancer, or degree of estrogen receptor (ER) or progesterone receptor (PgR) expression." (PMID 27149669, 2016).
breast cancer (continued). "In the past decades, several membrane-located proteins were discovered that could successfully be targeted, i.e. estrogen/progesterone receptor (ER/PR) in breast cancer patients and epidermal growth factor receptor (EGFR) in lung cancer patients." (PMID 26943581, 2016). "Invasive breast cancers that are positive for the estrogen receptor and/or the progesterone receptor can be managed systemically with a variety of endocrine agents, such as tamoxifen for premenopausal patients and tamoxifen or one of the aromatase inhibitors for postmenopausal patients." (PMID 28717716, 2016). "To date, treatment planning for breast cancer patients has been based on a histologic analysis of the primary tumor and the expression of molecular markers such as estrogen receptor (ER), progesterone receptor (PR), and human epidermal growth factor receptor 2 (HER2)." (PMID 27028212, 2016). "Others found that diets rich in fruits and salads, a food pattern traditionally high in polyphenols, was associated with a reduced risk of breast cancer, particularly estrogen and progesterone receptor negative breast cancers." (PMID 27608040, 2016). "ER+ PgR+ Ki-67- breast cancer cells were successfully recognized as nuclei with a purple color, indicating that light-field chromogenic triple immunostaining using these chromogens is suitable for use in searching for SOX2+ (or NANOG+) HIF-1α+ RNApII-S2P-/low cells in astrocytoma tissues." (PMID 26799577, 2016). "In this study, we evaluated 618 patients with ER-positive “low-risk” breast cancer (size ≤ 30 mm, lymph node-negative) for whom PgR was determined by IHC at one pathology laboratory." (PMID 27722840, 2016). "Furthermore, CA was greater in triple negative and HER2 amplified subtypes; in general, estrogen/progesterone receptor-positive breast cancers have a more favorable prognosis than HER2 amplified or triple negative cancers." (PMID 26832928, 2016). "Despite the advances in molecular classification of breast cancer, identifying of clinically relevant subgroups is still based on the status of estrogen and progesterone receptor (ER and PR) and human epidermal growth factor receptor 2 (HER2) along with clinicopathological variables." (PMID 26884644, 2016). "Furthermore, cut-off values for receptor negative vs. positive tumors need to be established and have already been determined for ESR1 and PGR in human breast cancer using a bDNA assay." (PMID 27649560, 2016). "Breast cancer is a heterogeneous tumor exhibiting five molecular types, classified by gene profiling and the expression of hormonal receptors such as estrogen receptor (ER), progesterone receptor (PR), and human epidermal growth factor (HER2)." (PMID 27242965, 2016). "In routine clinical practice, however, relying on immunohistochemical analysis of the estrogen receptor (ER), progesterone receptor and her2/neu receptor, breast cancer is subdivided into hormone receptor positive, her2/neu receptor positive, and (lack of all three receptors) triple negative." (PMID 27608009, 2016). "This paradox indicated that PgR status could be used to identify a unique phenotype of Luminal-B breast cancers." (PMID 26053183, 2015). "We focused on the MDA-MB231 breast cancer cell line representing triple-negative mesenchymal highly invasive human breast cancer cells and MCF-7 breast cancer cells, being positive for ER and PgR expression, but deficient for caspase-3, for comparison." (PMID 26383236, 2015). "This study examined the tissue composition and immunophenotypic profile of ERα, ERβ, PgR, HER2 and Ki-67 in tissue samples taken from clinically and radiologically normal breasts of women at high risk of breast cancer and assessed the relationship of these parameters with mammographic density." (PMID 26110820, 2015).